IL1B (interleukin 1 beta)
Diseases named in the same sentence as IL1B in open-access papers (continued):
Sharing a sentence is not in itself a finding about the gene and the disease.
ascariasis (1 paper, 2024). An infection that is caused by the roundworm Ascaris lumbricoides, many cases of which remain asymptomatic. "Furthermore, the study found elevated levels of IL-1β and TNFα, indicating that ascariasis increases susceptibility to Aspergillus sp." (PMID 39591259, 2024).
Asperger syndrome (1 paper, 2023). "Another study revealed distinct peripheral cytokine profiles in females (i.e., increased IL-1β, IL-7, and IL-12p40) and males (i.e., increased IL-1β, IL-3, IL-4, IL-5, IL-10, IL-12p40, IL-12p70, IL-18, and TNF-α) with Asperger syndrome." (PMID 37511467, 2023).
attention deficit-hyperactivity disorder (1 paper, 2012). A disorder characterized by a marked pattern of inattention and/or hyperactivity-impulsivity that is inconsistent with developmental level and clearly interferes with functioning in at least two settings (e.g. at home and at school). "Novel research has also demonstrated the involvement of IL-1β, IL-2, IL-8, and TNFα dysfunction in neurological diseases including attention-deficit hyperactivity disorder (ADHD) and delayed cognitive development." (PMID 22768323, 2012).
autonomic neuropathy (1 paper, 2022). An inherited or acquired peripheral neuropathy affecting the autonomic nervous system. "Factors of relevance described in the literature in DM include advanced glycated end-product deposition in the myocardium, myofibroblast ‘switching’, autonomic neuropathy, inflammation via TNF-alpha and IL-1b, renin–angiotensin system activation, and blood glucose levels." (PMID 35596784, 2022).
autosomal dominant polycystic kidney disease (1 paper, 2021). Autosomal dominant form of polycystic kidney disease. "In addition, the vaso-constrictive properties of IL-1β were linked to patients with autosomal dominant polycystic kidney disease (ADPKD)." (PMID 34445357, 2021).
avascular necrosis (1 paper, 2022). Necrotic changes in the bone tissue due to interruption of blood supply. "This study detected five target genes (IL-1β, STAT3, CAT, PTGS2, and HMOX1) to further study the effects of quercetin, luteolin, kaempferol, cryptotanshinone, and naringenin on the expression of related genes in steroid-induced avascular necrosis of the femoral head." (PMID 35915795, 2022).
bladder disorders (1 paper, 2023). "By an elevated level of IL-1β or TNF-α, DV can be separated from these bladder disorders." (PMID 36983336, 2023).
bone marrow failure (1 paper, 2020). "Interestingly, hampering the action of the inflammatory cytokine interleukin 1 beta (IL-1β), using IL-1 receptor blockade, avoids bone marrow failure." (PMID 32962238, 2020).
brain glioma (1 paper, 2025). A malignant glioma that involves the brain. "Nevertheless, the results on many plasma samples indicate the diagnostic value of IL-1β as a marker of brain glioma." (PMID 40429943, 2025). "In this work, matrix SPRi biosensors are used as a new analytical method to examine the levels of selected proteins (HIF-1α, ANG-2, and IL-1β) in plasma and tissue homogenates from patients with diagnosed brain glioma." (PMID 40429943, 2025). "This confirmed a statistically significant difference in concentrations between the grades of brain glioma only in the case of IL-1β." (PMID 40429943, 2025). "For each tested protein (HIF-1α, ANG-2, and IL-1β), an increase in concentration implies an increase in the chances of developing brain glioma." (PMID 40429943, 2025). "This allowed potential specific relationships to be identified between levels of the HIF-1α, ANG-2, and IL-1β proteins in brain glioma patients." (PMID 40429943, 2025).
bruxism (1 paper, 2025). Excessive clenching of the jaw and grinding of the teeth. "One study that evaluated the association of elevated GCF IL-1β levels with periodontal microinflammation caused by bruxism claimed that the expression of this cytokine could be a potential predictor for the periodontal diagnosis and prevention of further inflammation." (PMID 41149097, 2025).
bubonic plague (1 paper, 2016). A plague in which the bacteria have infected the lymphatic system. "We have reported that deletion of both YopM and YopJ in a fully virulent Y. pestis KIM1001 strain implicates increased IL-1β and IL-18 in vivo, and leads to significant attenuation following subcutaneous (s.c.)infection mimicking bubonic plague." (PMID 27911947, 2016).
campylobacteriosis (1 paper, 2021). Infections with bacteria of the genus campylobacter. "We mimicked subepithelial cytokine release in the epithelial cell model by adding the major cytokines found in campylobacteriosis, namely of IFN-γ, TNF-α and IL-1β." (PMID 33935732, 2021).
carditis (1 paper, 2025). "From a translational perspective, IL-6 and IL-8 may serve as potential diagnostic biomarkers, while targeting IL-1β or CXCR3-dependent signaling could represent therapeutic avenues to mitigate inflammation associated with carditis." (PMID 41305420, 2025).
CARS syndrome (1 paper, 2021). "In this report, we showed that IL-1β-primed MSC attenuated HS-induced early organ injury and dysfunction and reduced the SIRS/CARS syndrome as shown by a decrease in plasma cytokine concentrations and phenotypic activation of circulating CD11bc+ cells." (PMID 34353366, 2021).
catalepsy (1 paper, 2013). A nervous system disorder characterized by diminished responsiveness and consciousness, and rigidity of the body. "Thus, in this study we attempted to investigate the effect of chronic administration of 8-OH-DPAT on 6-OHDA-induced catalepsy and possible involvement of TNF-α, IL-1β and IL-6." (PMID 24570834, 2013). "The role of pro-inflammatory cytokines in the pathogenesis of PD has been shown in several studies, although the effect of chronic administration of 5-HT1A receptor agonists on 6-OHDA-induced catalepsy and the role of cytokines such as TNF-α, IL-1β and IL-6 has not been clearly studied yet." (PMID 24570834, 2013).
cellulitis (1 paper, 2023). Inflammation of the dermis and subcutaneous tissues caused by a bacterial infection. "NSTI patients have higher levels of IL-1β than patients with other cutaneous infections such as cellulitis." (PMID 37946314, 2023).
Cerebellar atrophy (1 paper, 2011). Cerebellar atrophy is defined as a cerebellum with initially normal structures, in a posterior fossa with normal size, which displays enlarged fissures (interfolial spaces) in comparison to the foliae secondary to loss of tissue. "These overactive microglia can produce highly neurotoxic factors, including superoxide, TNF-α, and IL-1β, which are likely to perpetuate neuronal death and lead to overt cerebellar atrophy in iPLA2β-/- mice." (PMID 22046428, 2011). "Moreover, glial cell activation and the elevation in TNF-α and IL-1β expression occurred before apparent cerebellar atrophy." (PMID 22046428, 2011).
cerebellar degeneration (1 paper, 2022). Degeneration of the cerebellum. "To explore the mechanism underlying the protective effect of MCC950 in METH-induced cerebellar degeneration, we conducted an immunoblotting analysis of NLRP3 pathway proteins including NLRP3, ASC, Caspase-1, Cleaved Caspase-1 (P20), IL-1β and mature IL-1β." (PMID 35431795, 2022). "Collectively, these findings suggest that mature IL-1β secretion mediated by NLRP3-ASC-Caspase 1 may be a critical step in METH-induced cerebellar degeneration and highlight the neuroprotective properties of inflammasome inhibition in cerebellar degeneration." (PMID 35431795, 2022).
cervical adenosquamous carcinoma (1 paper, 2022). An uncommon carcinoma arising from the cervix. "Notably, for histological type, CAMK2A, CYBB, IL1A, IL1B, and SLC25A5 were found to be upregulated in patients with cervical squamous cell carcinoma compared with those having cervical adenosquamous carcinoma (P < 0.05)." (PMID 36253777, 2022).
cervical tumor (1 paper, 2013). "Although IL-1β was recently identified to be targeted by high-risk HPV as a central hub within the network of innate immunity and down-regulated in cervical tumors, our knowledge about its function and regulation in the context of HPV-induced carcinogenesis is still rudimentary." (PMID 23935506, 2013). "We analyzed IL-1β regulation in immortalized keratinocytes that harbor the HPV16 E6 and/or E7 oncogenes as well as HPV-positive cervical tumor cells." (PMID 23935506, 2013).
cherubism (1 paper, 2025). Cherubism is a rare, self-limiting, fibro-osseous, genetic disease of childhood and adolescence characterized by varying degrees of progressive bilateral enlargement of the mandible and/or maxilla, with clinical repercussions in severe cases. "This study focuses on the consequences of Caspase-1 deletion leading to IL-1β alterations in the pathogenesis of cherubism." (PMID 39951467, 2025). "In the present study, we aimed to disentangle the impact of IL-1β in a Sh3bp2 KI mouse model of cherubism and determine whether IL-1β could be a novel therapeutic target to rescue the bone phenotype." (PMID 39951467, 2025). "Alternatively, IL-1β may not be instrumental in the pathogenesis of cherubism and its upregulation only reflects the hypersensitivity of macrophages." (PMID 39951467, 2025).
choroidal degeneration (1 paper, 2022). "Recent findings suggest that exposure to the pro-inflammatory cytokine IL-1β is associated with choroidal degeneration in the early stages of retinopathy and that fetuses exposed only to IL-1β display a persistent postnatal infiltration of inflammatory cells." (PMID 34168272, 2022).
Chronic diarrhea (1 paper, 2022). The presence of chronic diarrhea, which is usually taken to mean diarrhea that has persisted for over 4 weeks. "Our data also suggested that FMT intervention obviously increased the level of IL-10 and decreased the levels of IL-6, IL-8, IL-1β, and IFN-γ in chronic diarrhea monkey serum during the intervention, especially on Day-8." (PMID 36551772, 2022).
chronic kidney failure (1 paper, 2024). "In an in vivo study involving uremic rats with chronic kidney failure, it was observed that rats fed a diet containing 0.1% Mg experienced increased pro-inflammatory cytokines like TNF-α, IL-1β, and IL-6, resulting in the induction of oxidative stress." (PMID 39200118, 2024).
chronic liver failure (1 paper, 2020). Liver failure that develops slowly and gradually for some time, possibly for years, often as the result of cirrhosis, or malnutrition. "IL-1β was reported to be the major inductive cytokine of NGAL by NF-kB activation in an experimental acute-on-chronic liver failure model." (PMID 32997091, 2020).
chronic thromboembolic pulmonary hypertension (1 paper, 2024). Chronic thromboembolic pulmonary hypertension (CTEPH) is characterized by the persistence of thromboemboli in the form of organized tissue obstructing the pulmonary arteries. "Also, in patients with chronic thromboembolic pulmonary hypertension (CTEPH), different cytokines showed increased levels, such as IL-1β, IL-2, IL-4, IL-6, IL-8 and IL-10." (PMID 38612795, 2024).
clear cell sarcoma (1 paper, 2025). A rare malignant neoplasm with melanocytic differentiation characterized by the presence of polygonal or spindle shaped clear cells. "Moreover, BCP‐ALL, Ph+ ALL, Ph‐like‐ALL, and MLL‐ALL demonstrated the highest IL‐1β expression when compared to all cancer types, except for a singular case of clear cell sarcoma." (PMID 40104043, 2025).
CLN5 disease (1 paper, 2017). "Next, to further investigate the relationship between IL-1β and neurogenesis in CLN5 disease, we treated WT and Cln5-KO NPCs with recombinant IL-1β, or with an IL-1β blocking antibody." (PMID 28733362, 2017).
clostridium difficile infection (1 paper, 2015). Symptomatic infection due to the spore-forming bacterium clostridium difficile. "An IL-1β-mediated positive-feedback loop has been reported to play a protective role against Clostridium difficile infection." (PMID 26176534, 2015).
CO poisoning (1 paper, 2025). "In summary, this MR study provides genetic evidence supporting a potential causal role of IL-10, IL-1β, and IL-13 in the pathogenesis of CO poisoning." (PMID 40988268, 2025).
coal worker pneumoconiosis (1 paper, 2023). "In vitro experiments have demonstrated that IL-1β and TNF-α secretion by alveolar macrophages is considered an early inflammatory response that leads to progressive tissue damage and fibrosis in coal worker pneumoconiosis (CWP)." (PMID 36675056, 2023).
collagenous colitis (1 paper, 2014). A type of microscopic colitis of unknown etiology. "There was significantly increased production of the proinflammatory cytokines IFN-γ, IL-17A, IL-6, and IL-1β in the presence of CM generated by culture of denuded biopsies (DNB-CM) from the colon of collagenous colitis patients, compared to DNB-CM from noninflamed controls." (PMID 25332518, 2014).
colonic adenoma (1 paper, 2025). "Similarly, ATG5-silenced human colonic adenoma cells show significantly elevated IL-1β production under LPS stimulation." (PMID 41463800, 2025).
congenital toxoplasmosis (1 paper, 2015). Toxoplasma infection that is present from birth. "The outcomes obtained in our study may suggest that the presence of mutated T allele at the analyzed IL1B SNP plays a protective function against the development of congenital toxoplasmosis." (PMID 26385345, 2015). "Considering our outcomes, as presented in this paper, the GC heterozygotic status at the IL6 −174 G>C SNP, as well as the presence of C alleles at both IL6 and IL1B +3954 C>T SNPs, seems to have been involved in the occurrence of congenital toxoplasmosis in the studied fetuses and neonates." (PMID 26385345, 2015). "So far, several studies have shown some contribution of the encoded IL6 and IL1β cytokines to immune responses against T. gondii, although no such research has been performed for congenital toxoplasmosis." (PMID 26385345, 2015).
convulsion (1 paper, 2024). A rapid and repeated body muscle contract that results in an uncontrolled shaking of the body. "IL-1β was positively correlated with HHV-6 copy number in saliva of children with convulsion." (PMID 38590522, 2024).
Cowden syndrome (1 paper, 2019). "However, in the absence of functional PTEN in Cowden syndrome patients, romidepsin still potently suppressed IL-1β production, indicating that the cytokine-suppressive effects of romidepsin are independent of PTEN." (PMID 30728075, 2019).
cowpox (1 paper, 2023). A mild, eruptive skin disease of milk cows caused by cowpox virus, with lesions occurring principally on the udder and teats. "SPI-2 inhibits the proteolytic activity of caspase 1 (Interleukin 1 beta, IL-1b, converting enzyme) and granzyme B. Cells infected with the orthopoxviruses cowpox and rabbitpox are resistant to cytolysis via these mechanisms." (PMID 37759793, 2023).
crescentic glomerulonephritis (1 paper, 2021). A histopathologic term for a pattern of diseases characterized by extensive crescent formation in the glomeruli; patients present clinically with rapid deterioration of renal function, and possible progression to end-stage renal failure within weeks or months. "Gene deletion of IL-1 Type 1 Receptor (IL1R1) or IL-1β demonstrated that IL-1β but not IL-1α contributed to crescent formation and inflammatory cell recruitment in murine anti-GBM crescentic glomerulonephritis." (PMID 34307414, 2021).
cryoglobulinemia (1 paper, 2014). Cryoglobulinemia is a type of vasculitis that is caused by abnormal proteins (antibodies) in the blood called 'cryoglobulins.' At cold temperatures, these proteins become solid or gel-like, which can block blood vessels and cause a variety of health problems. "Moreover, these double-high patients had significantly higher positivity of anti-nuclear antibody, cryoglobulinemia, and lymphotropic HCV and higher amounts of IL1-β, IL21, IL23." (PMID 24905921, 2014).
cystic tumors (1 paper, 2024). "Cystic tumors exhibited higher expression of IL1B, IL6, IL10, and TNF (all P < 0.05) than non-cystic tumors." (PMID 38965454, 2024).
deafness (1 paper, 2020). An inherited or acquired condition characterized by the complete loss of the ability to hear from one or both ears. "In noise-induced deafness, proinflammatory cytokines or chemokines, including TNF-α, IL-1β, IL-6, Icam-1, and Ccl2, were increased in cells of the stria vascularis or lateral wall." (PMID 33505961, 2020).
diffuse cutaneous Leishmaniasis (1 paper, 2017). A form of LEISHMANIASIS, CUTANEOUS caused by Leishmania aethiopica in Ethiopia and Kenya, L. pifanoi in Venezuela, L. braziliensis in South America, and L. mexicana in Central America. "Patients with localized cutaneous lesion (LCL) exhibit predominant expression of iNOS, IL-1β, IL-6, MCP-1, TNF-α, and IFN-γ, while anergic diffuse cutaneous leishmaniasis (ADCL) lesions are characterized by the presence of IL-4, IL-5, IL-10, and MIP-1α and the low expression of iNOS." (PMID 28959260, 2017).
Dravet syndrome (1 paper, 2022). "The intracellular analysis of patients with Dravet syndrome revealed increased levels of pro-inflammatory cytokines, including IL-1β, in cells following the stimulation of monocytes with an in vitro vaccine." (PMID 35054141, 2022).
drug dependence (1 paper, 2021). "Also, IL-1β levels significantly increased in the analysis of the sample MA abuse increases the level of TNF-α in the central nervous system, and the nucleus accumbens; this is closely related to drug dependence, highly expresses TNF-α mRNA and protein." (PMID 35002809, 2021).
dystroglycanopathy (1 paper, 2016). "Thus, IL-1β appears to be a RAPA-insensitive modulator of inflammation in dystroglycanopathy muscle." (PMID 27257474, 2016).
dystrophinopathies (1 paper, 2017). "Some of these studies showed that the functional blockade of NF-κB or the inflammatory cytokines, such as TNF-α, IL-6 and IL-1β are a specific therapeutic strategy for the treatment of dystrophinopathies." (PMID 28787441, 2017).
ectodermal dysplasia (1 paper, 2022). "In HC rat lungs at P14, the number of ectodermal dysplasia (ED)-1- and TUNEL-positive cells and level of inflammatory cytokines such as interleukin (IL)-1α, IL-1β, IL-6, and TNF-α were significantly increased." (PMID 35743045, 2022).
egg allergy (1 paper, 2023). A food allergy that is an allergy or hypersensitivity to dietary substances from the yolk or whites of eggs, causing an overreaction of the immune system which may lead to severe physical symptoms. "Furthermore, children with persistent hen’s egg allergy continued to show higher levels of IL-6, IL-1β and IL-8 in unstimulated CD3-depleted cells compared to children who developed tolerance to hen’s egg at the end of follow-up." (PMID 36756279, 2023). "Following LPS stimulation, IL-6 and IL-1β production was more elevated in both persistent and transient hen’s egg allergy in comparison to healthy controls at follow-up but increased production of TNF-α and IL-8 was unique to infants with persistent hen’s egg allergy." (PMID 36756279, 2023).
Ehrlich tumor (1 paper, 2024). "The serum level of the cytokines IL-1β and TNF-α was determined in mice injected with the solid Ehrlich tumor." (PMID 38774541, 2024). "Mice with the solid Ehrlich tumor that was treated with chloroquine and healed from malaria infection presented an elevation of serum level of IL-1β, but not TNF-α, compared to the control." (PMID 38774541, 2024). "The results show that the Ehrlich tumor did not induce an increase in serum levels of IL-1β and TNF-α compared to the control group." (PMID 38774541, 2024). "Mice injected with the solid Ehrlich tumor and infected with Plasmodium berghei presented an elevation of serum level of IL-1β, but not TNF-α." (PMID 38774541, 2024). "The serum level of IL-1β, but not TNF-α, increased in mice with the solid Ehrlich tumor and treated with chloroquine." (PMID 38774541, 2024).